SLC2A1 (solute carrier family 2 member 1)
Diseases named in the same sentence as SLC2A1 in open-access papers (continued):
Sharing a sentence is not in itself a finding about the gene and the disease.
glioma (91 papers, 2010 to 2025). A benign or malignant brain and spinal cord tumor that arises from glial cells (astrocytes, oligodendrocytes, ependymal cells). "Particularly, ECs from glioma exclusively expressed a series of transmembrane transport-associated genes, including SLC2A1, BSG, SLC7A1, and SLC7A5, suggesting that ECs in brain tumors were still involved in retaining the brain-blood barrier." (PMID 39345334, 2024). "In this work, it was found that SLC2A1 was overexpressed in glioma samples, and SLC2A1 expression was negatively associated with miR-152-3p expression in glioma patients." (PMID 31492194, 2019). "Furthermore, SLC2A1 expression was increased in glioma tissues and negatively associated with miR-152-3p expression in glioma samples (P < 0.001)." (PMID 31492194, 2019). "Mechanically, circRNA ZNF609 enhances the expression of glucose transporter SLC2A1 by inhibiting miR-378b, thereby promoting glycolysis and cell survival in glioma." (PMID 39272133, 2024). "The expression of miR-378b was negatively correlated with ZNF609 and SLC2A1 and ZNF609 expression was positively associated with SLC2A1 in the clinical glioma samples." (PMID 34520391, 2021). "Long non-coding RNA LINC00174 enhances tumor progression and glycolysis in glioma via miR-152-3p/SLC2A1 axis." (PMID 34520391, 2021). "N-acetylglucosaminyltransferase I enhances migration and proliferation of glioma cells by increasing SLC2A1." (PMID 34520391, 2021). "The inhibition of miR-378b or the enhancement of SLC2A1 reversed ZNF609 depletion-regulated glioma cell proliferation in vitro." (PMID 34520391, 2021). "In our present study, we demonstrated a pro-metastatic role of circZNF609 in glioma, determined an interaction between miR-378b and SLC2A1, and established the role of this regulatory axis in circZNF609-mediated glycolysis during glioma progression." (PMID 34520391, 2021). "Meanwhile, SLC2A1 plays an essential function in the regulation of glycolysis and progression of glioma." (PMID 34520391, 2021). "Systematic study concerning the biological function and mechanism of SLC2A1 in glioma will be an important part of our future studies." (PMID 31492194, 2019). "The results displayed that miR-152-3p mimic inhibited cell proliferation, migration, invasion and glycolysis in glioma cells, while SLC2A1 knockdown abolished the effect of miR-152-3p mimic on glioma cells." (PMID 31492194, 2019). "The results reveal that LINC00174 promotes glioma cell proliferation, migration, invasion and glycolysis through regulating miR-152-3p/SLC2A1 axes." (PMID 31492194, 2019). "Additionally, the inhibitory effect of knocking down linc00174 in glioma cells can be reversed by miR-152-3p inhibitor or overexpression of SLC2A1." (PMID 38967893, 2024). "A previous study reported that glioma cells with IDH1 mutation produce 2-hydroxyglutarate, which promotes HIF-1α degradation, accompanied by the downregulation of glycolysis-related genes including SLC2A1, PDK1, LDHA, and SLC16A3." (PMID 33627136, 2021). "It implies that ZNF609 modulates glioma progression by miR-378b/SLC2A1 axis." (PMID 34520391, 2021). "Moreover, the ZNF609 and SLC2A1 expression were enhanced and miR-378b expression was reduced in the clinical glioma samples." (PMID 34520391, 2021). "MiR-378b and SLC2A1 may just one of the mechanisms of ZNF609-meidated glioma progression and other potential mechanisms are needed to investigate to comprehensively understand the function of ZNF609 in glioma." (PMID 34520391, 2021). "Therefore, we concluded that ZNF609 contributed to cell survival and glycolysis of glioma by targeting miR-378b/SLC2A1 axis." (PMID 34520391, 2021). "LINC00174 promotes glioma progression via miR-152-3p/SLC2A1 axis." (PMID 34671615, 2021). "Mechanically, miR-378b was sponged by ZNF609 and targeted SLC2A1 in glioma cells." (PMID 34520391, 2021). "Our data showed that miR-378b was sponged by ZNF609 and targeted SLC2A1 in glioma cells." (PMID 34520391, 2021).
glioma (continued). "The miR-152-3p inhibitor or the SLC2A1 overexpression could rescue the anti-tumor effect of LINC00174 knockdown on glioma cells." (PMID 31492194, 2019). "SLC2A1 is overexpressed in several different types of cancer, including liver cancer, lung cancer, endometrial cancer, oral cancer, breast cancer, gastric cancer and glioma." (PMID 31492194, 2019). "LINC00174 accelerated carcinogenesis of glioma via sponging miR-1523-3p and increasing the SLC2A1 expression, which could be considered as a molecular target for glioma diagnosis and therapy." (PMID 31492194, 2019). "Although a lot of studies demonstrates that SLC2A1 mediated the glucose transport in cancer cells, few studies focus on the detail function and the mechanism of SLC2A1 in glioma, and the pathways related with SLC2A1 in cancer progression are also rarely studied." (PMID 31492194, 2019). "However, it is not clear whether LINC00174 can regulate the expression of microRNA-152-3p and SLC2A1 to play a role in glioma." (PMID 31492194, 2019). "Therefore, the objective of this study is to investigate whether LINC00174 promotes glycolysis and glioma progression by regulating the miR-152-3p/SLC2A1 axes." (PMID 31492194, 2019). "The increased expression of HK2, PFKM, SLC2A1, and PKM2 induced by TGF-β has been observed in several types of cancer, including gliomas, particularly under hypoxic conditions." (PMID 40943648, 2025). "The solute carrier family 2 facilitated glucose transporter member 1 (SLC2A1), and the solute carrier family 25 members (SLC25A6) transcripts and proteins were up-regulated in glioma versus normal brain tissues." (PMID 37762371, 2023). "We showed by IFCA that membrane concentration of GLUT1/SLC2A1, one of the glucose transporters present in high grade gliomas, was increased in living U-87 MG cells by glucose starvation compared to the same cells grown in presence of glucose." (PMID 32443613, 2020). "Similarly, It has been demonstrated that LINC00174 contributes to the carcinogenesis of glioma and further promotes glycolysis via miR-152-3p modulation, involving GLUT1 (SLC2A1) overexpression." (PMID 35912242, 2022).
gastric cancer (83 papers, 2008 to 2025). A primary or metastatic malignant neoplasm involving the stomach. "SLC2A1 is considered an early marker of malignant tumors, overexpressed in esophageal squamous cell carcinoma, gastric carcinoma, and colon cancer, among others, often in association with poor prognosis." (PMID 31816603, 2019). "This study demonstrated that compared with low SLC2A1, high SLC2A1 was related to worse clinical outcomes, such as advanced T and N stage, large tumor size, lymphatic invasion, mutation, copy number gain/amplification and hypomethylation in patients with gastric cancer." (PMID 33735188, 2021). "Earlier research has indicated that elevated levels of Slc2a1 correlate with poorer outcomes in lung, breast, and stomach cancers 38-40." (PMID 40084244, 2025). "High expression of SLC2A1 can affect the prognosis of gastric cancer by suppressing CD8+ T cells and B cells." (PMID 36712872, 2022). "SLC2A1 is highly expressed in many kinds of cancer, and the overexpression of SLC2A1 can promote the growth and metastasis of cancers, such as liver, lung, endometrial, oral, breast, and gastric cancers." (PMID 36358765, 2022). "Studies have shown that the overexpression of SLC2A1 in cervical cancer, gastric cancer, esophageal cancer, and oral cancer can advance the proliferation of cancer cells." (PMID 35399515, 2022). "Along with in vivo studies, ATRA-based clinical trials in gastric cancer with high SLC2A1 expression are needed in the future." (PMID 33735188, 2021). "The aim of this study was to analyze the survival and genetic changes/immune profiles in patients with gastric cancer with high SLC2A1 expression and to provide treatment for improving prognosis." (PMID 33735188, 2021). "Disease-free survival and disease-specific survival according to SLC2A1 expression in 279 patients with gastric cancer (Eulji Hospital cohort)." (PMID 33735188, 2021). "In summary, the study demonstrated that high SLC2A1 expression was statistically associated with poor DFS/DSS as well as copy number gain/amplification and hypomethylation in patients with gastric cancer in both our EHC and TCGA databases." (PMID 33735188, 2021). "Given the link between SLC2A1 and retinoic acid, we investigated the sensitivity to ATRA between gastric cancer cell lines with high SLC2A1 expression and those with low SLC2A1 expression." (PMID 33735188, 2021). "In gastric cancer with high SLC2A1 expression, the decrease in immune cells and immune components, such as CD8 T cells and B cells and TCR, BCR and PD-L1 expression, is related to type III (intrinsic) induction." (PMID 33735188, 2021). "Correlation between clinicopathological parameters and SLC2A1 expression in 279 gastric cancer patients (Eulji Hospital cohort)." (PMID 33735188, 2021). "Further studies are necessary to prove the relationship between SLC2A1 and glucose in gastric cancer cells." (PMID 33735188, 2021). "In survival analyses, compared with low SLC2A1 expression, high SLC2A1 expression was associated with worse DFS and DSS in patients with gastric cancer." (PMID 33735188, 2021). "In the drug response analysis, the drug ATRA inhibited gastric cancer cell lines with high SLC2A1 expression." (PMID 33735188, 2021). "We believe that medical oncologists and researchers will be interested in the role of SLC2A1 in contributing to the energy supply for the development and growth of gastric cancer and that our results will facilitate further studies." (PMID 33735188, 2021). "We assessed the response to conventional chemotherapy drugs, including fluorouracil, a compound of fluoropyrimidine S-1, oxaliplatin, and all−trans−retinoic acid (ATRA), in gastric cancer cell lines with high SLC2A1 expression." (PMID 33735188, 2021). "ATRA, known as retinoic acid, inhibited gastric cancer cells with high SLC2A1 expression in this study, but there are some considerations for the clinical application of this drug." (PMID 33735188, 2021).
gastric cancer (continued). "This study investigated the clinicopathologic parameters, the proportion of immune cells and gene sets affecting SLC2A1 expression in 279 and 415 patients with gastric cancer from the Eulji Hospital cohort and The Cancer Genome Atlas, respectively." (PMID 33735188, 2021). "Previous studies reported that SLC2A1 expression was up-regulated in non-small cell lung cancer, colon cancer, and gastric cancer, and mediated the glucose transport in cancer cells." (PMID 31492194, 2019). "Our results indicate SLC2A1 exhibits a pivotal role in tumor growth, metastasis and glucose metabolism, and also suggest SLC2A1 as a promising target for gastric cancer therapy." (PMID 26193257, 2015). "The expression of SLC2A1 is upregulated in human tumors, such as colon and gastric cancers." (PMID 39297018, 2024). "SLC2A1 was identified as an adverse prognostic factor of gastric cancer." (PMID 35251577, 2022). "Moreover, PD-L1, as a marker for determining the use of immunotherapy, was highly expressed in gastric cancer with high SLC2A1 expression." (PMID 33735188, 2021). "On the basis of the GDSC data, we analyzed drug sensitivity patterns in 8 gastric cancer cell lines with high SLC2A1 expression based on ATRA, known all−trans−retinoic acid, fluorouracil, a compound of oral fluoropyrimidine S-1, and oxaliplatin, known as XELOX." (PMID 33735188, 2021). "ATRA was effective in gastric cancer cell lines exhibiting high SLC2A1 expression." (PMID 33735188, 2021). "In addition, our analytic workflow for SLC2A1 will contribute to designing future experimental studies and future drug development for patients with gastric cancer." (PMID 33735188, 2021). "The present study aimed to assess whether SLC2A1 is related to the clinicopathological parameters and survival of patients with gastric cancer in our Eulji Hospital cohort (EHC) and those from the TCGA database." (PMID 33735188, 2021). "Treatment involving the use of SLC2A1 could contribute to better clinical management/research for patients with gastric cancer." (PMID 33735188, 2021). "miR‐148b function directly targeting glucose transporter SLC2A1, may strengthen the role of miR‐148b as a target for early clinical diagnosis and treatment for gastric cancer." (PMID 28440026, 2017). "Furthermore, it has been revealed that all-trans-retinoic acid (ATRA) could be a candidate drug for the treatment of gastric cancer patients with high SLC2A1 expression and resistance to conventional chemotherapy." (PMID 35938001, 2022). "An in vitro study to evaluate the inhibitory effect of ATRA in gastric cancer cell lines with high SLC2A1 expression revealed that a high concentration (over 102 mM) of retinoic acid significantly suppressed the growth of MKN-45 cells with high SLC2A1 expression." (PMID 33735188, 2021). "The negative association between SLC2A1 and immune cells may be important for designing immunotherapies for the treatment of gastric cancer." (PMID 33735188, 2021). "SLC2A1 overexpression correlates with the suppression of CD8+ T cells and B cells in gastric cancer." (PMID 36275774, 2022). "Consistently, it has been found that hypoxia-related genes CA9, NDRG1, SLC2A1, P4HA1 and ENO1 induced EMT in hepatocellular carcinoma, bladder cancer, laryngeal cancer and gastric cancer, respectively." (PMID 34136390, 2021). "Gastric cancer cell lines with high SLC2A1 expression were more sensitive to oxaliplatin than those with low SLC2A1 expression, but the difference was not statistically significant." (PMID 33735188, 2021). "An RXR selective ligand, bexarotene, was not effective in gastric cancer cell lines exhibiting high SLC2A1 expression (data not shown)." (PMID 33735188, 2021). "However, interactive molecules and pathways of targeted drugs for gastric cancer with high SLC2A1 expression have not yet been elucidated." (PMID 33735188, 2021).
gastric cancer (continued). "Unlike the responses in cell lines with high SLC2A1 expression, the therapeutic responses in patients with gastric cancer may be highly heterogeneous and affected by various microenvironments and immune components, which could have effects on clinical applications." (PMID 33735188, 2021).
glioblastoma (76 papers, 2012 to 2026). The most malignant astrocytic tumor (WHO grade IV). "SLC2A1 was over-expressed in the glioblastoma cancer stem cell (CSC) control as well." (PMID 27786256, 2016). "Next, we determined the impact of Aurora kinase A on key glycolytic transporters (SLC2A1) and enzymes (HK2, LDHA), some of which are upregulated in glioblastoma as compared to normal brain tissue." (PMID 34471141, 2021). "In order to further understand the relevance of elevated GLUT3 in GBM biology, we analyzed the Ivy Glioblastoma Atlas Project database and found GLUT3 (SLC2A3), but not GLUT1 (SLC2A1), expression was significantly elevated at the leading edge of GBMs." (PMID 33843470, 2021).
melanoma (75 papers, 2008 to 2026). A malignant, usually aggressive tumor composed of atypical, neoplastic melanocytes. "Consistent with scRNA-seq results, SLC2A1 was upregulated in the selected persister subpopulation, supporting its association with the stress-like transcriptional program in melanoma resistance." (PMID 41000875, 2025). "Decreasing SOX2 expression in melanoma cells was associated with a shift towards glycolysis, with increased lactate production and higher expression of SLC2A1/3 (also known as GLUT1/3), and hexokinase 2, which help import glucose and catalyze glycolysis in cells." (PMID 34831420, 2021). "The increased glucose up-take in melanoma is sustained by the increased expression of transporter protein GLUT1 (SLC2A1)." (PMID 32509589, 2020). "The results revealed that the CSTB, GBF1, TYR, RAC1, SLC2A1 and NOTCH3-coding proteins were significantly enriched in melanoma samples, while CEBPB-coding protein had low expression in melanoma samples." (PMID 37217516, 2023). "Five of nine identified ER stress-related genes, CEBPB, TYR, SLC2A1, NOTCH3 and RAC1, have been reported to engage in melanoma malignant behavior regulation." (PMID 37217516, 2023). "For instance, melanoma cells upregulate the gene expression of glucose transporter isoform 1 and 3 (GLUT1/SLC2A1 and GLUT3/SLC2A3) to take up a high amount of glucose." (PMID 35565278, 2022).
hepatocellular carcinoma (73 papers, 2007 to 2025). A malignant tumor that arises from hepatocytes. "In order to evaluate the expression level of hub genes (HRAS, SLC7A11 and SLC2A1) in hepatocellular carcinoma, we conducted immunohistochemical (IHC) analysis." (PMID 37051544, 2023). "In this study, we blocked the function of SLC2A1 using BAY-876 and discovered that it could suppress the expression of gluconeogenesis and glycogenolysis-related genes in hepatocellular carcinoma cells." (PMID 37443106, 2023). "Among the eight mRNAs in the model, the up-expressions of TKTL1, KDELR3, PFKP, SLC2A1, and PGF in hepatocellular carcinoma were confirmed in previous experimental studies, while the over-expression of SAP30 in HCC was reported in an earlier computational study." (PMID 36362375, 2022). "We obtained a prognostic signature including eight hypoxia genes (ENO2, KDELR3, PFKP, SLC2A1, PGF, PPFIA4, SAP30, and TKTL1) and further established a hypoxia-related prognostic ceRNA network including 17 lncRNAs, six miRNAs, and seven mRNAs for hepatocellular carcinoma." (PMID 36362375, 2022). "In hepatocellular carcinoma (HCC), METTL3 expression positively correlated with glycolysis genes SLC2A1, HK2, PFKM and PKM." (PMID 33669361, 2021).